TIMP1 (TIMP metallopeptidase inhibitor 1)
Diseases named in the same sentence as TIMP1 in open-access papers (continued):
Sharing a sentence is not in itself a finding about the gene and the disease.
periodontitis (continued). "Finally, there was a significant difference in the levels of aMMP-8, the rate of MMP-8 activity, tMMP-8, MPO, PMN elastase, and TIMP-1 between the base level of (untreated) patients with periodontitis and 13 periodontally and systemically healthy controls." (PMID 39273368, 2024). "Likewise, the ROC curve showed a statistically significant diagnostic accuracy (sensitivity and specificity) with an AUC of 1.000 (p value = 0.0001) for both the MMP-8/TIMP-1 and MMP-9/TIMP-1 combinations when comparing periodontal health and periodontitis S1." (PMID 36292174, 2022). "In addition, in contrast to other biomarkers, TIMP-1 differentiated periodontitis S1 and S3 (AUC: 0.738)." (PMID 36292174, 2022). "Interestingly, when using ratios, the diagnostic potential increased with MMP-8/TIMP-1 (AUC of 0.986, p value = 0.0001) and MMP-9/TIMP-1 (AUC of 1.000, p value = 0.0001) between periodontal health and periodontitis." (PMID 36292174, 2022). "Therefore, the aim of this systematic review was to evaluate the scientific literature regarding TIMP‐1 concentrations in oral fluids of patients suffering from periodontitis or gingivitis in comparison to healthy individuals." (PMID 34850390, 2022). "Similarly, these cut-off points of both MMP-8/TIMP-1 and MMP-9/TIMP-1 combinations showed the highest sensitivity and specificity (1.000 each) for differentiation between control and S1 periodontitis." (PMID 36292174, 2022). "When HGF was higher than this concentration, then TIMP-1 at levels lower than 89.27 ng/ml could achieve increased identification of periodontitis cases to an accuracy of 97.2% with one false positive." (PMID 33742017, 2021). "TIMP-1 levels were significantly reduced in the periodontitis group compared to both gingivitis (0.56-fold) and health (0.49-fold) groups, while the other 9 protein levels were up-regulated in subjects with periodontitis." (PMID 33742017, 2021). "The ratio of aMMP-8, measured by the IFMA method, and TIMP-1 could successfully differentiate between periodontitis and healthy smoking subjects as well." (PMID 30305812, 2018). "The ROC curve showed that MMP-8, MMP-9, TIMP-1, MMP-8/TIMP-1, and MMP-9/TIMP-1 had statistically significant diagnostic accuracy, with areas under the curve (AUCs) of 0.892, 0.844, 0.920, 0.986, and 1.000, respectively, when distinguishing periodontitis from the controls." (PMID 36292174, 2022). "Moreover, TIMP-1 values were elevated in these lower stages of periodontitis severity." (PMID 31892956, 2019). "The effects of anti-infective treatment (scaling and root planning) in 13 periodontitis patients were monitored by aMMP-8, the rate of aMMP-8 RFU activity, tMMP-8, MPO, PMN elastase, TIMP-1, calprotectin, and IL-6 as well as by clinical periodontal parameters." (PMID 39273368, 2024). "Periodontitis was found to predict increased MMP-9 and tissue inhibitor of matrix metalloproteinases (TIMP-1) and their ratio MMP-9/TIMP-1." (PMID 35448062, 2022). "Meanwhile, the AUCs between periodontal health and periodontitis S1 for MMP-8, MMP-9, and TIMP-1 were 0.964 (p value = 0.0001), 0.938 (p value = 0.001), and 0.902 (p value = 0.002), respectively." (PMID 36292174, 2022). "Salivary levels of miR-1246 in patients with chronic periodontitis were positively correlated with the levels of IL-1β, IL-6, IL-17, TNF-α, MMP-1, MMP-8, TIMP-1, PLI, GI, PD, and AL (P < 0.05)." (PMID 35942384, 2022). "L. reuteri supplementation was useful in chronic periodontitis patients, whose gingival crevicular fluids showed a decrease in MMP-8 levels and an increase in TIMP-1 compared to the placebo group." (PMID 35408849, 2022). "The salivary levels of miR-1246, IL-1β, IL-6, IL-17, TNF-α, MMP-1, MMP-8, and TIMP-1 and the periodontal indexes PLI, GI, PD, and AL in the chronic periodontitis group were significantly higher than those in the healthy control (P < 0.05)." (PMID 35942384, 2022).
periodontitis (continued). "For discriminating gingivitis vs periodontitis groups, the predictor variables resulting from the CART analysis included HGF, TIMP-1, MMP-9/TIMP-1 ratio and OPG." (PMID 33742017, 2021). "Significantly higher levels of TIMP-1 were observed in LT recipients with a healthy periodontium, compared to recipients with stage II or III periodontitis, in our study." (PMID 33916950, 2021). "Using doxycycline dosage as SDD (sub antimicrobial dose doxycycline) for the treatment of periodontitis, Chouy etal., found that doxycycline reduced the MMP-9 concentration and increased TIMP-1 concentration." (PMID 33841538, 2020). "Both increased and decreased TIMP-1 levels were reported in GCF and gingival tissues of patients with periodontitis." (PMID 24886536, 2014). "Many physiological functions of TIMP-1 are closely tied to the functions of MMPs, and an improper balance of MMP and TIMP production correlates with pathological conditions such as periodontitis, arthritis, tumor growth, and metastasis." (PMID 26464855, 2014). "The aim of this study was to further investigate and gain a deeper understanding of the relationship between periodontitis, potential oral fluid biomarkers including mouthrinse aMMP-8, aMMP-9, tMMP-8, tMMP-9, PMN elastase, MPO, TIMP-1, IL-6, Calprotectin, and prediabetes." (PMID 39353614, 2025). "In this study, we aimed to (i) detect Td-dentilisin and MMP-8 immunoexpression levels in gingival tissue samples of patients with periodontitis compared with periodontally healthy gingivae to (ii) assess the MMP-8, MMP-2, MMP-7, TIMP-1, and IL-1β mRNA expressions in the diseased vs. healthy gingiva." (PMID 38786309, 2024). "The increase in MMP‐8/ TIMP‐1 ratio in these studies was predominantly related to increased salivary MMP‐8 levels in periodontitis patients and not necessarily to decreased TIMP‐1 concentrations in saliva." (PMID 34850390, 2022). "In general, our results showed that TIMP‐1 levels do not differ significantly between periodontitis/ gingivitis patients and healthy individuals in both saliva and GCF." (PMID 34850390, 2022). "However, when comparing the ratios of MMP-8/TIMP-1 and MMP-9/TIMP-1, the results showed significant differences in all periodontitis groups in comparison to the control group." (PMID 36292174, 2022). "The plotted ROC curves showed a good predictor value for the MMP-9/TIMP-1 ratio, the (MMP-8 + MMP-9)/TIMP-1 ratio and the MMP-8 + MMP-9 sum (as top three), followed by the MMP-8/TIMP-1 ratio, HGF, MMP-2, and OPG for differentiation of periodontitis versus gingivitis conditions (AUC ≥ 0.85)." (PMID 33742017, 2021). "In addition to MMP-8, patients with severe periodontitis have been reported to have significantly higher levels of IL-1β and an elevated MMP-8/TIMP-1 molar ratio." (PMID 33916950, 2021). "The plotted ROC curves showed a good predictor value of the MMP-9/TIMP-1 ratio, (MMP-8 + MMP-9)/TIMP-1 ratio, and HGF (as top three), followed by the MMP-9, MMP-2, MMP-8 + MMP-9 sum and the MMP-8/TIMP-1 ratio, for differentiation of periodontitis versus health conditions (AUC ≥ 0.95)." (PMID 33742017, 2021). "In serum, the MMP‐8, MMP‐9, and TIMP‐1 concentrations were slightly higher in the no‐periodontitis patients but the differences were not statistically significant." (PMID 29744196, 2017). "We investigated serum and saliva concentrations of matrix metalloproteinases, MMP‐8, MMP‐9, and MMP‐13, and their tissue inhibitor TIMP‐1, in a group of patients with and without periodontitis from Sweden." (PMID 29744196, 2017). "In saliva, MMP‐8, MMP‐9, and TIMP‐1 values were slightly higher in the periodontitis patients, but again, the differences between groups were not significant." (PMID 29744196, 2017). "The objective of this study was to investigate the levels and associations of salivary MMP-8, -9, MPO and tissue inhibitors of metalloproteinase (TIMP)-1 in myocardial infarction (MI) patients and controls with or without periodontitis." (PMID 26132583, 2015).
periodontitis (continued). "However, they failed to differentiate periodontitis S1 to S3, except for TIMP-1, which exhibited a potential to discriminate between periodontitis S1 and S3." (PMID 36292174, 2022). "Nevertheless, even when TIMP-1 levels were > 89.27 ng/ml and HGF concentration were higher than 2.753 pg/ml, no further splits were made and the accuracy of determining periodontitis patients was as high as 94.1%." (PMID 33742017, 2021). "This study evaluated the gene expression of IL-1ß, IL-6, TNF-α, MMP-1, MMP-2, MMP-8, MMP-9, TIMP-1, and TIMP-2 in the gingival tissue of individuals with periodontitis or peri-implantitis compared to individuals without periodontal or peri-implant disease." (PMID 33291232, 2020).
Stroke (47 papers, 2009 to 2025). Sudden impairment of blood flow to a part of the brain due to occlusion or rupture of an artery to the brain. "Serum MMP-8 concentrations have been directly associated with risk of future CVD, and the concentrations of MMP-8 and TIMP-1 showed a positive correlation with the severity of stroke." (PMID 39917664, 2024). "An association between MMP9/TIMP1 ratio and the most severe ischemic stroke subtype was found in a cohort of 126 untreated stroke patients." (PMID 26074872, 2015). "The present study is in line with previous observations in patient samples of associations of TIMP-1 with all-cause and cardiovascular mortality, but extends these to a population-based setting and identifies a robust relation to stroke risk." (PMID 21283828, 2011). "Higher TIMP-1 levels were mainly related to higher risk of stroke and cardiovascular mortality, and higher MMP-9 levels mainly to risk of non-cardiovascular mortality." (PMID 21283828, 2011). "All relations except those of TIMP-1 to stroke risk were attenuated by adjustment for cardiovascular disease risk factors." (PMID 21283828, 2011). "Additionally, levels of MMP-8 and MMP-8/TIMP-1 ratio assessed in a cross-sectional study in patients with first IS and in a control group became independently associated with stroke." (PMID 36835040, 2023). "We then hypothesized that higher TIMP‐1 levels in the acute phase could increase the risk of post‐stroke cognitive impairment." (PMID 32431079, 2020). "In particular, higher TIMP-1 levels were related to higher risk of stroke and cardiovascular death." (PMID 21283828, 2011). "In previous studies, elevated TIMP-1 levels have been determined as a highly significant, independent predictor for stroke, MI, and cardiovascular death, and to correlate with the severity of stroke." (PMID 39917664, 2024). "Our data reveal ambiguous trends regarding changes in MMP9 and TIMP1 level or MMP9/ TIMP1 during post-stroke rehabilitation and their implications for functional status, as well as their influence on cognition and depression recovery in stroke patients." (PMID 38891934, 2024). "We observed marked differences between WT and CD36 KO of multiple well-described inflammatory players in neonatal stroke and hypoxia–ischemia, including down-regulation of Tlr4, Timp1, Csf-1 and CD68." (PMID 35148760, 2022). "Varying levels within the first 25 h were also described for MMP-9 and TIMP-1 in experimental stroke." (PMID 34899557, 2021). "For example, during the acute phase of stroke, some soluble factors, such as tissue inhibitor of metalloproteinase 1 (TIMP-1) and pentraxin 3 (PTX3), are secreted in and/or near the damaged area to ease the breakdown of the BBB." (PMID 33260683, 2020). "We also found several MMP-related genes, such as MMP2 and TIMP1, to be significantly downregulated in post-stroke muscle." (PMID 32629989, 2020). "Our analysis found that ischaemic patients with both higher serum TIMP‐1 (≥184.2 ng/mL) and MMP‐9 (≥462.6 ng/mL) levels had higher risk of post‐stroke cognitive impairment." (PMID 32431079, 2020). "In this context, the MMP-9/TIMP-1 ratio was investigated extensively in multiple neurological conditions such as multiple sclerosis, stroke/ischemia, and Alzheimer's disease." (PMID 33384653, 2020). "Several genes belonging to the ECM-receptor interaction such as TIMP1 and cell adhesion molecules are dysregulated at 24 h post-stroke indicating an acute BBB breakdown." (PMID 32300291, 2020). "This advantage provides us a convenient opportunity to study the prognostic utility of TIMP‐1 for post‐stroke cognitive impairment." (PMID 32431079, 2020). "The purpose was to prospectively investigate the relationship between serum TIMP‐1 with post‐stroke cognitive impairment." (PMID 32431079, 2020). "TIMP-1 overexpression also ameliorates MMP-9 mediated blood-brain barrier leakage in models of stroke, traumatic brain injury and cerebral ischemia." (PMID 29459817, 2017).
Stroke (continued). "Such elevated TIMP-1 expression was observed in conjunction with elevated MMP-9 levels at 24 h following stroke onset." (PMID 26973468, 2016). "Both mrProANP and A-FaBP have been proposed as diagnostic and prognostic biomarkers in adults with stroke We found higher A-FaBP levels in the septic subjects with neurologic dysfunction, but only MMP-9/TIMP-1 ratio was associated with 6-month outcome." (PMID 27089280, 2016). "ADMA was positively correlated with IL-6 and CRP at 3 and 7 days and with TIMP-1 at 6 and 24 hours, 3 and 7 days after stroke onset." (PMID 23158556, 2012). "SDMA was positively correlated with MCP-1 at 6 hours and 3 and 7 days, with IL-6 at 3 and 7 days and with TIMP-1 at 7 days after stroke onset." (PMID 23158556, 2012). "TIMP-1 levels were mainly related to risks of cardiovascular mortality and stroke (HR per standard deviation 1.22, 95% CI 1.09–1.37; and 1.18, 1.04–1.35; respectively)." (PMID 21283828, 2011). "Relations of TIMP-1 level to risks of cardiovascular mortality and stroke were slightly stronger in this subsample than in the total sample." (PMID 21283828, 2011). "Importantly, Nbce1iΔAstro stroke brains revealed an anti-inflammatory cytokine profiling signature, marked by increased TIMP-1 expression." (PMID 40762246, 2025). "This study implies that TIMP1 may be a key regulator involved in the occurrence and development of acute post-stroke inflammation." (PMID 40604895, 2025). "Hence, the aim of this study was to assess the prognostic value of MMP-9, TIMP-1, and MMP-9/TIMP-1 ratio, and of the expression of their genes, as markers of recovery in stroke patients." (PMID 38891934, 2024). "Similarly, there is an increased expression of TIMP-1 via astrocytes post-CNS injury (neuroinflammation and stroke) in a mouse model." (PMID 39329731, 2024). "Importantly, including serum TIMP‐1 to the traditional factors models significantly improved the predictive value of post‐stroke cognitive impairment." (PMID 32431079, 2020). "Interestingly, mRNA expression analysis showed an upregulation of Timp1 in the ipsilateral hemisphere after stroke." (PMID 28290150, 2018). "Data from an in vitro stroke model of a human brain microvascular endothelial cell line show favorable effect of statin pretreatment on the MMPs metabolism, mainly by induced the expression and secretion of TIMP-1 and TIMP-2." (PMID 29435135, 2018). "However, just as MMP-9 levels are elevated following stroke, the expression of TIMP-1, the endogenous inhibitor of MMP-9, has also been shown to be dysregulated following stroke." (PMID 26973468, 2016). "Specifically, the MMP9/ Timp1 was elevated on the seventh day of stroke, which might provide a biomarker of prognosis." (PMID 27213359, 2016). "The observed relations were of modest magnitude, and the relations of TIMP-1 to stroke risk were not explained to any major extent by established cardiovascular disease risk factors or C-reactive protein." (PMID 21283828, 2011). "Our study revealed that exercise preconditioning suppressed the HIF‐VEGF‐Notch pathway through TIMP1, enhanced the body's antioxidant stress and antiapoptotic capacity, and exerted neuroprotective effects on CIRI, thereby providing a basis for the prevention of stroke in high‐risk populations." (PMID 39364701, 2024). "Furthermore, the MMP-9/TIMP-1 ratio has been proposed as a marker of stroke." (PMID 26973468, 2016). "The observation that the relation of TIMP-1 to stroke risk was independent of C-reactive protein levels, as well as other cardiovascular risk factors, may indicate that extracellular matrix metabolism is an important process per se." (PMID 21283828, 2011). "Relations of TIMP-1 level to stroke risk were independent of these covariates." (PMID 21283828, 2011). "TIMP-1 levels have also been shown to be a powerful predictor for some cardiovascular disease (CVD) outcomes, like myocardial infarction (MI) and stroke, and ultimately cardiovascular death." (PMID 39917664, 2024).
Stroke (continued). "Treatment with TPO also reduces stroke-induced cortical MMP-9 and TIMP-1 expression and enzymatic activity." (PMID 32341206, 2020). "Furthermore, TIMP-1 has anti-apoptotic effects and may be neuroprotective when given after stroke." (PMID 29343288, 2018). "From clinical perspective, the results gain importance especially when TIMP-1 and MMP-9 together are recently under intense investigation as a biomarker for stroke and cardiovascular death in humans." (PMID 24146955, 2013). "Clinical studies have shown that TIMP-1 can be applied to treat BBB dysfunction in brain injury, and in experimental stroke models, the lack of TIMP-1 exacerbates the disruption of the BBB." (PMID 40869300, 2025). "Simvastatin administered during the first week of IS inhibited the serum MMP-9 activity, although the early treatment with simvastatin (started at first day after stroke onset) influenced neither MMP-9 nor TIMP-1 levels." (PMID 36835040, 2023). "Moreover, circulating TIMP‐1 and MMP‐9 had been reported to be increased in stroke, multiple sclerosis and other neurological diseases." (PMID 32431079, 2020). "Interestingly, we observed a joint effect of serum TIMP‐1 and MMP‐9 on post‐stroke cognitive impairment." (PMID 32431079, 2020). "In keeping with the role of MMP-9 and TIMP-1 in the pathogenesis of stroke, mild hypothermia provided protection from ischemia/reperfusion injury via decreasing the expression of MMP-9 and TIMP-1." (PMID 26973468, 2016). "The in vivo effects of the increase in MMP-9 may therefore be determined by its activity relative to TIMP-1, as has been suggested for the use of MMP-9 as a clinical biomarker in stroke." (PMID 22507553, 2012). "In our stroke cohort, day 1 MMP-9 and MMP-9/TIMP-1 ratio correlated with acute DWI lesion volumes." (PMID 21871109, 2011). "No sex differences were reported for plasma levels of tissue inhibitor metalloproteinase 1 (TIMP-1) and insulin-like growth factor 1 (IGF-1) 1 day after stroke, matrix metalloproteinase 2 (MMP2) within 2 days after stroke, and matrix metalloproteinase 9 (MMP9) 2 days and 1 month after stroke." (PMID 34858141, 2021). "In order to discern if the increased activity of MMP-9 and tPA that we see in the stroke EE group was due to changes in expression of respective ECM proteases, mRNA levels of Mmp9, as well as Adamts4, Tpa, and their inhibitors (respectively, Timp1, Timp3, and Neuroserpin) were studied by RT-qPCR." (PMID 28290150, 2018). "Transient global cerebral ischemia led to TIMP-1 expression within 4 h of onset within the dentate gyrus of the hippocampus and progressed to involve other regions of the hippocampus including CA1 by 24 h post-stroke, a region especially vulnerable to ischemic injury." (PMID 26973468, 2016). "Levels of MCP-1, CRP and TIMP-1 did not significantly differ between stroke patients and controls." (PMID 23158556, 2012).